IMPA2 (inositol monophosphatase 2)
Diseases named in the same sentence as IMPA2 in open-access papers:
IMPA2 is named in the same sentence as 26 diseases in open-access papers, as found by Europe PMC text mining. Sharing a sentence is not in itself a finding about the gene and the disease. The quoted sentences say what the papers report.
bipolar disorder (8 papers, 2010 to 2025). A disorder of the brain that causes unusual shifts in mood, energy, activity levels and the ability to carry out day-to-day tasks. "Among its targets is the inositol monophosphatase gene IMPA2, which has also been associated with risk of bipolar disorder in some family studies, and our observations offer a cellular signalling pathway in which PO activity and IMPA2 gene expression converge." (PMID 20567601, 2010). "Second, genetic studies suggest that the presence of a specific set of SNPs within the IMPA2 gene promoter associates with elevated risk for bipolar disorder in some family studies." (PMID 20567601, 2010). "We propose that altered transcriptional control of inositol synthetic and metabolic genes, particularly IMPA2, could contribute to elevated risk of bipolar disorder." (PMID 20567601, 2010). "Finally, we show that this PO mediated regulation of gene expression is conserved in human cells where among its targets is IMPA2, a gene associated with risk in some bipolar disorder patient family studies." (PMID 20567601, 2010). "Similarly, lithium inhibits IMPA1 and IMPA2 activity, pointing to the broad impact of lithium on suppression of IP metabolism, with IMPA2 additionally identified as a susceptibility gene in bipolar disorder, schizophrenia and febrile seizures." (PMID 41032702, 2025). "Despite the higher frequency of psychiatric symptoms in MRT59 patients, bipolar disorder has been associated with changes in IMPA2 and not in IMPA1." (PMID 37508980, 2023). "IMPA2 irregularity has always been proven to contribute to the pathophysiology of bipolar disorder." (PMID 37140233, 2023). "The association between PLCD1 and IMPA2 in Group 1 in each age interval also is of interest because IMPA2, which dephosphorylates myo-inositol monophosphate within the “PI cycle”, has been proposed as the preferred target of lithium in the treatment bipolar disorder." (PMID 26168237, 2015). "Indeed, IMPA2 may participate in the development of SCZ and bipolar disorder and its promoter may be a hot spot harbouring IMPA2 variants." (PMID 27748550, 2017). "In summary, this study found that the T allele of rs2075824 in IMPA2 promoter region possibly contributed to risk for SCZ in Han Chinese individuals by elevating transcription, providing evidence for the hypothesis that some susceptibility may be common to both SCZ and bipolar disorder." (PMID 27748550, 2017).
schizophrenia (5 papers, 2014 to 2025). A major psychotic disorder characterized by abnormalities in the perception or expression of reality. "Our data suggest that a promoter polymorphism of IMPA2 possibly contributed to risk for schizophrenia by elevating transcription activity in Han Chinese individuals." (PMID 27748550, 2017). "By stratifying males and females, we found a gender‐specific association for IMPA2 and schizophrenia: the T allele of rs2075824 was more frequent in male cases compared with male controls [P = 1.4 × 10−4, OR (95% CI) = 1.33 (1.15–1.55)]." (PMID 27748550, 2017). "Inositol Monophosphatase 2 (IMPA2) is hypothesized to be involved in the phospholipase C signalling pathway, which mediates the action of several neurotransmitters and hormones and which may underlie schizophrenia." (PMID 36980961, 2023). "Carriers of the “AA” genotype for IMPA2 rs669838 are also more likely to have a history of suicide attempts in comparison to C-allele carriers, and IMPA2 or a nearby gene may contribute to the overall genetic risk for schizophrenia." (PMID 27661109, 2016). "Previous studies with biological and genetic evidence indicate that the myo‐inositol monophosphatase 2 (IMPA2) gene may influence schizophrenia." (PMID 27748550, 2017).
cervical cancer (4 papers, 2020 to 2023). A primary or metastatic malignant neoplasm involving the cervix. "The present study is proposed to identify the potential cancer-promoting action of IMPA2 in cervical cancer and explore possible pathways controlled by IMPA2 to further understanding the molecular mechanisms underlying cervical cancer." (PMID 32409648, 2020). "IMPA2, as a potential oncogene, was well established in this study to regulate the onset of apoptosis in cervical cancer cells." (PMID 37140233, 2023). "This indicates that inhibition of IMPA2 expression can synergize with paclitaxel-induced apoptosis and thus promote the sensitivity of cervical cancer cells to paclitaxel." (PMID 37140233, 2023). "Cervical cancer continues to be a concern, and the prognosis of locally advanced cervical cancer remains poor.IMPA2 was previously identified as a potential oncogene and regulator of tumor apoptosis." (PMID 37140233, 2023). "To further demonstrate that IMPA2 can generate drug resistance by affecting paclitaxel-mediated apoptosis, we selected cervical cancer cells with stable knockdown ofIMPA2 and control cells." (PMID 37140233, 2023). "CCK-8 assay, clone formation assay, wound healing assay, transwell assay, and tumor formation in nude mice were performed to demonstrate the effect of IMPA2 in cervical cancer proliferation and metastasis." (PMID 32409648, 2020). "Wound-healing assay and transwell migration assay were conducted to examine the effect of IMPA2 on the migration and invasion of cervical cancer cells." (PMID 32409648, 2020). "JNK 1/2/3 and p38 remained unchanged, suggesting that MAPK/ERK signaling pathway take part in IMPA2-induced tumorigenesis of cervical cancer." (PMID 32409648, 2020). "IMPA2 silencing slowed the speed with which both cervical cancer cells filled the scratch, in comparison to the control in an obvious manner." (PMID 32409648, 2020). "Short hairpin RNA (shRNA)-mediated IMPA2 silencing significantly inhibited proliferation and colony-forming abilities of cervical cancer cells, while IMPA2 overexpression had little impact." (PMID 32409648, 2020). "We suspect that IMPA2 can be a promoting element in the early stage of cervical cancer, but the further migration or invasion still need other contributing factors." (PMID 32409648, 2020). "Expression of IMPA2 was also compared among cervical cancer cell lines and normal cervical epithelial cell line to prove the overexpression." (PMID 32409648, 2020). "On the contrary, our data of RNA sequencing (RNA-seq) showed an obvious upregulation of IMPA2 in cervical cancer." (PMID 32409648, 2020). "Here, we discussed the role of IMPA2 and found that IMPA2 promoted the ability of proliferation, metastasis, and in vivo tumorigenesis of cervical cancer cells." (PMID 32409648, 2020). "We therefore performed proteomics analysis to look for clues of molecular regulation by IMPA2 in cervical cancer." (PMID 32409648, 2020). "Further proteomic analysis was performed to discuss the possible mechanisms regulated by IMPA2 in cervical cancer." (PMID 32409648, 2020). "In the present study, IMPA2 was upregulated in cervical cancer tissues when compared with pair matched normal tissues, which is consistent with the dataset of IMPA2 from TCGA." (PMID 32409648, 2020). "The role of IMPA2 in cervical cancer cells were detected after transfected with overexpressed plasmids and small interfering RNA (siRNA) lentivirus." (PMID 32409648, 2020). "As there are few published articles about the role of IMPA2 gene in cervical cancer, this study performed both in vitro and in vivo studies to discuss the relationship between cervical cancer and IMPA2." (PMID 32409648, 2020). "Our results suggest that IMPA2 is a potential therapeutic target for cervical cancer treatment." (PMID 37140233, 2023).
cervical cancer (continued). "The results showed that IMPA2 gene expression was upregulated in cervical cancer." (PMID 32409648, 2020). "Moreover, increased protein level of IMPA2 was also observed in paired cervical cancer samples by immunohistochemistry (IHC)." (PMID 32409648, 2020). "IMPA2 is significantly overexpressed in cervical cancer samples (P < 0.0001)." (PMID 32409648, 2020). "In conclusion, IMPA2 is a novel tumor promotor that regulates ERK MAPK in cervical cancer." (PMID 32409648, 2020). "Therefore, we suspect that upregulated ERK decreased cervical cancer progression by activating apoptosis in IMPA2 silencing cells." (PMID 32409648, 2020). "Collectively, the present study is the first report to demonstrate that IMPA2 may act as an oncogene in cervical cancer." (PMID 32409648, 2020). "IMPA2 downregulated ERK phosphorylation to promote cervical cancer." (PMID 32409648, 2020). "In conclusion, IMPA2 acts as an oncogene in the proliferation and migration of cervical cancer." (PMID 32409648, 2020). "Our previous study first showed that IMPA2 might promote cervical cancer progression." (PMID 37140233, 2023). "We found that FR180204 treatment significantly reversed the IMPA2-induced decrease in cell viability, cell migration and invasion in Hela cell, suggesting that activation of the ERK signaling pathway may result in inhibitory of proliferation and migration induced by IMPA2 in cervical cancer." (PMID 32409648, 2020). "This is contrary to our speculation on the role of IMPA2 in cervical cancers." (PMID 32409648, 2020). "Our results also suggest that paclitaxel can kill tumor cells by regulating the expression of IMPA2/AIFM2, and this mechanism provides a new target for the major role of paclitaxel as an anti-cervical cancer drug in cancer chemotherapy." (PMID 37140233, 2023). "Therefore, we speculated that IMPA2 may be a cancer-promoting gene in cervical cancer." (PMID 32409648, 2020). "Thus, silencing IMPA2 could step down proliferation and metastasis of cervical cancer cells." (PMID 32409648, 2020). "IMPA2 is an important paralog of IMPA1 and plays an oncogenic role in cervical cancer." (PMID 35796646, 2023). "Further real-time PCR was used to determine the IMPA2 expression pattern in 61 pairs of cervical cancer tissues and their matched adjacent non-tumor cervical tissues." (PMID 32409648, 2020). "Overexpression of IMPA2 failed to enhance the cell growth in both cervical cancer cells." (PMID 32409648, 2020).
carcinoma in situ of cervix (1 paper, 2020). "And as introduced previously, IMPA2 was identified upregulated in carcinoma in situ of cervix." (PMID 32409648, 2020).
diabetes mellitus (1 paper, 2016). A metabolic disorder characterized by abnormally high blood sugar levels due to diminished production of insulin or insulin resistance/desensitization. "First, we did not take into consideration the association of conventional risk factors, such as smoking, hypertension, obesity, elevated triglyceride and cholesterol levels, diabetes mellitus and dyslipidemia, for IS risk with IMPA2 polymorphisms." (PMID 27661109, 2016).
glioma (1 paper, 2025). A benign or malignant brain and spinal cord tumor that arises from glial cells (astrocytes, oligodendrocytes, ependymal cells). "Notably, IMPA2, SOD3, CD274, ITPRIPL1, and RAC2 displayed relatively negative correlations across multiple cancers, including glioma." (PMID 40852729, 2025).
ischemic stroke (1 paper, 2016). A stroke disorder caused by obstruction of blood flow to the brain, due to thrombotic (local blood clot formation) or embolic (due to a blood clot or other material traveling from another site) event. "Genetic association analysis has suggested that IMPA2 is a susceptibility gene for ischemic stroke (IS)." (PMID 27661109, 2016).
kidney tumors (1 paper, 2022). "In this study, we also showed that IMPA2 was important in kidney tumors." (PMID 35127943, 2022).
mental disorder (1 paper, 2022). A disease that has its basis in the disruption of mental process. "Eight genes are implicated in viral (SEC14L1, JMJD6, SRSF2, TMPRSS2, MX1, MX2) or bacterial (COL8A1, SPIRE1) infections, seven genes (MFSD11, METTL23, CTTNBP2, BACE2, IMPA2, MPPE1 and GNAL) are involved in mental disorders and one gene (MGAT5B) is related to the Golgi complex." (PMID 35581286, 2022).
renal carcinoma (1 paper, 2025). A carcinoma arising from the epithelium of the renal parenchyma or the renal pelvis. "IMPA2 expression has been shown to be suppressed by miR-25 in the setting of renal cancer, a micro RNA that is well known to be involved in the progression of many types of cancers, suggesting miRNA-regulated modulation of IMPA2 expression across various cancer settings." (PMID 41032702, 2025).
renal cell carcinoma (1 paper, 2025). "Previous studies have shown that downregulation of the IMPA2 gene inhibits autophagy initiation in renal cell carcinoma, facilitating the proliferation and migration of renal cell carcinoma cells." (PMID 40362506, 2025).
Stroke (1 paper, 2020). Sudden impairment of blood flow to a part of the brain due to occlusion or rupture of an artery to the brain. "At gene level, few were differentially expressed: ALDH2, ALOX5AP, F13A1, and IMPA2 (males, all stroke); ITGB3 (females, cardioembolic); ADD1 (males, atherosclerotic); F13A1, IMPA2 (males, lacunar); and WNK1 (females, lacunar)." (PMID 33193047, 2020).
cancer (9 papers, 2020 to 2025). A tumor composed of atypical neoplastic, often pleomorphic cells that invade other tissues. "While inositol monophosphatases have been extensively studied in neuropsychiatric disorders, emerging evidence has further linked IMPA1 and IMPA2 to the pathogenesis of various cancers." (PMID 41032702, 2025). "Previously, we demonstrated that low-level IMPA2 expression is associated with high risk for cancer metastasis and poor prognosis in TCGA ccRCC patients." (PMID 32235551, 2020). "However, there is only one published article clearly demonstrated the relationship between IMPA2 expression and cancer progression." (PMID 32409648, 2020). "Thus, it is inferred that hsa-mir-21 may modulate the reduced expression of the IMPA2 gene in the C2 subtype, promoting cancer cell proliferation and migration in this subtype." (PMID 40362506, 2025). "For example, there was increased IMPA2 expression in the malignant fraction of the EEC cohort and increased chromatin accessibility of a cancer-specific dRE within the IMAP2 locus." (PMID 39229264, 2024). "However, the mechanism of IMPA2 in cancer is utterly unknown." (PMID 32409648, 2020). "Although, to date, there are limited reports on the role of IMPase in cancer development and metastatic progression, we recently reported that the posttranscriptional repression of IMPA2, but not IMPA1, promotes metastatic progression in ccRCC." (PMID 32235551, 2020).
tumor (5 papers, 2020 to 2023). "In this study,IMPA2, a novel gene we previously found from transcriptomics analysis, was proved to be a potential tumor-promoting gene." (PMID 37140233, 2023). "The IMPA2 silencing group showed significantly smaller tumor size (P = 0.0274) and lighter average weight (P = 0.0123) than the control group." (PMID 32409648, 2020). "After knockdown ofIMPA2, the IC50 values of paclitaxel were decreased in both HeLa and SiHa cells, indicating that inhibition of IMPA2 expression could enhance the sensitivity of tumor cells to paclitaxel." (PMID 37140233, 2023). "Consistently, silencing of IMPA2 suppressed tumor formation in BALB/c nude mice." (PMID 32409648, 2020). "During tumor progression, CAPZA1, GRB2, NF2EL3, PLEKHO1, SIGLEC1, and UBE2Z were expressed at higher levels in late-stage KIRC, whereas EMX2, FUCA1, IMPA2, and RORC were expressed at higher levels in early-stage KIRC." (PMID 35127943, 2022). "CAPZA1, HLA-E, IMPA2, NFE2L3, PLEKHO1, SIGLEC1, and UBE2Z were expressed at higher levels in tumor tissues, whereas EMX2, FGL2, FUCA1, and GRB2 were expressed at lower levels in tumor tissues." (PMID 35127943, 2022).
infection (1 paper, 2022). The state of being infected such as from the introduction of a foreign agent such as serum, vaccine, antigenic substance or organism. "Although Leptospira was the infection with more genes found in the significant genomic window, few genes are linked to each other (IMPA2, MPPE1, and GNAL—TAF5 and USMG5)." (PMID 35581286, 2022).
neurodegenerative disease (1 paper, 2020). A disorder of the central nervous system characterized by gradual and progressive loss of neural tissue and neurologic function. "Most of the studies agreed that inhibition of IMPA2 might induce IP3 accumulation and /or inositol depletion, which can finally regulate autophagy to help treat neurodegenerative diseases or bipolar disorders." (PMID 32409648, 2020).
neurological disorders (1 paper, 2022). "Indeed, identified genes are implicated in viral (SEC14L1, JMJD6, SRSF2, TMPRSS2, MX1, MX2) bacterial (COL8A1, SPIRE1), and neurological disorders (MFSD11, METTL23, CTTNBP2, BACE2, IMPA2, MPPE1 and GNAL), or in the functions of the Golgi complex (MGAT5B), organelle where viral envelope is occurred." (PMID 35581286, 2022).
IMPA2 also shares sentences with these, for which no sentence is quoted: autism (1 paper); cervical squamous cell carcinoma (1); Clear Cell Renal Cell Carcinoma (1); colon cancer (1); COVID-19 (1); dyslipidemia (1); Hypertension (1); hypothyroidism (1); Obesity (1).